ALB (albumin)
Diseases named in the same sentence as ALB in open-access papers (continued):
Sharing a sentence is not in itself a finding about the gene and the disease.
acute kidney injury (continued). "Low albumin within two postoperative days was an independent risk factor for acute kidney injury and increased length of hospital stay in patients undergoing TKA." (PMID 33939393, 2020). "SUCRA ranking revealed that gelatin, balanced crystalloid, saline, and iso-oncotic albumin had a lower risk of acute kidney injury than L-HES and H-HES." (PMID 33317590, 2020). "In a retrospective cohort study using a propensity score methodology, albumin administration was associated with a dose-dependent risk of acute kidney injury (AKI)." (PMID 32111230, 2020). "SUCRA showed iso-oncotic albumin, and balanced crystalloids were associated with less acute kidney injury than HES and gelatin." (PMID 33317590, 2020). "Synthetic colloids were substituted by albumin solution in LDLT donors from January 2013 at our institution due to the potential risk of acute kidney injury (AKI) associated with their use22,23." (PMID 30808903, 2019). "Colloids, such as albumin 4%, are recommended in patients at risk or with pre-existent renal failure and low albumin levels." (PMID 31277296, 2019). "Hyperoncotic albumin-exposed patients showed greater risk of acute kidney injury compared to controls (OR 1.10, 95% CI 1.04, 1.17." (PMID 30564306, 2018). "Early exposure to hyperoncotic albumin in postoperative shock appeared to be associated with acute kidney injury." (PMID 30564306, 2018). "Odds ratios for the association between admission serum albumin levels and hospital acquired acute kidney injury (HAKI) occurrence." (PMID 29927987, 2018). "Proportional odds logistic regression, multivariable logistic regression or Cox proportional hazard regression models measured association between hyperoncotic albumin and acute kidney injury (AKI), hepatic injury, ICU days, and mortality." (PMID 30564306, 2018). "Over the 12-month study period, 17 cases associated with low serum albumin in 53%, acute kidney injury in 94%, and thrombocytopenia in 18% were treated." (PMID 27642522, 2016). "In embryology, thus, extrahepatic expression of albumin is well established, but renal albumin mRNA expression in the adult kidney is only associated with acute kidney injury." (PMID 25874770, 2015). "A high sensitivity C-reactive protein to albumin ratio (hs-CRP/Alb) predicts mortality risk in patients with acute kidney injury." (PMID 25793462, 2015). "Low serum albumin, one of the important nutritional predictors, is associated with mortality and morbidity in renal failure patients." (PMID 27433541, 2014). "Outside of pregnancy, the use of hyperoncotic albumin seemed associated with development of acute renal failure." (PMID 25593752, 2014). "In conclusion, the findings of this meta-analysis support the use of albumin for preventing paracentesis-induced circulatory collapse and reducing the risk of death and renal failure in cirrhotic patients with infections limited to SBP." (PMID 24222902, 2013). "A secondary analysis of 794 septic patients with acute kidney injury undergoing continuous renal replacement therapy in Korea showed that each 1 g/dL increase in albumin level was independently associated with a 25% and 27% reduction in the risk of death at 28 and 90 d, respectively." (PMID 41264595, 2025). "Additionally, in a separate study of patients with non-Hodgkin lymphoma (NHL) receiving CD19-targeted CAR-T cell therapy, lower pretreatment serum ALB levels were associated with an elevated risk of acute kidney injury (AKI)." (PMID 41479909, 2025). "Several factors, including citrate in blood transfusion, increased phosphate concentration, renal failure, lower albumin levels, and vitamin D deficiency, may contribute to decreased calcium levels in patients with critical illnesses." (PMID 35743797, 2022). "Drainage of less than 5 L could require human albumin administration in case of concomitant of acute-on-chronic liver failure (ACLF) or in patients at high risk of renal failure development." (PMID 34830508, 2021).
acute kidney injury (continued). "In addition, the extent of renal failure is less prominent in this patient group probably explaining the missing association between renal function impairment and lower serum albumin values." (PMID 34840504, 2021). "The findings from our study are consistent with previous reports regarding the effects of hormonal contraceptives on renal failure, as various epidemiological studies have shown an association between hormonal contraceptive use and renal failure (urinary albumin loss)." (PMID 33728065, 2021). "A retrospective cohort study (N = 1,051,441 patients) undergoing elective total hip and knee arthroplasties showed that 6% Hetastarch (HES 450/0.7), which is the first-generation HES, and 5% albumin were associated with an increased risk of acute renal failure compared to crystalloid." (PMID 32783070, 2020). "Also, the 12 patients who showed complete response and marked serum creatinine decline after receiving only albumin as a corrective measure for the pre-renal causes of renal failure were excluded." (PMID 32076410, 2020). "Compared to the normal group, the risk of renal failure increased by the albumin level decline: the HRs were 2.99 (95% CI, 1.36-6.61, p = 0.007) for the mild group, 6.03 (95% CI, 3.05-11.95, p < 0.001) for the moderate group, and 13.74 (95% CI, 6.63-28.44, p < 0.001) for the severe group." (PMID 30911552, 2019). "Our study suggests that exposure to hyperoncotic albumin during the first 48 h of perioperative shock may be associated with an increased risk of acute kidney injury, particularly among post-cardiac surgery patients." (PMID 30564306, 2018). "However, other observational cohort studies of resuscitation have suggested increased risks of acute kidney injury (AKI) associated with hyperoncotic albumin in shock." (PMID 30564306, 2018). "Woman less than 45 years of age had an almost two-fold increase in malignancy, were more likely to have glomerulonephritis, obstruction or interstitial disease as their cause of renal failure, have a lower serum albumin and hemoglobin and were 5.7% less likely to initiate dialysis with a fistula." (PMID 25780605, 2014). "The serum albumin concentration may be directly altered, as results to loss albumin through damaged glomeruli in case of renal failure." (PMID 22849573, 2012). "Similarly, renal failure in cirrhotics is reversible if the precipitating causes can be treated effectively and by use of combination of vasoconstrictors and albumin." (PMID 21994871, 2011). "While the association between decreased serum albumin (ALB) levels and increased risk of acute kidney injury (AKI) is well established, the risk of death among patients with AKI with low serum ALB levels is unclear." (PMID 37946135, 2023). "Thus, serum albumin could be a better prognostic risk factor or biomarker for imported malaria than liver enzyme, as abnormal liver function impaired synthesis and acute kidney injury, resulting in an increased albuminuria." (PMID 36439238, 2022). "The base value of the ET model is E f(x) = 0.05, the patient transfusion albumin, corresponding to f(x) = 0.11; patient had acute kidney failure, corresponding to f(x) = 0.09." (PMID 40454154, 2025). "We searched PubMed, Web of Science, and Scopus from their inception to the end of August 2025 using a strategy combining controlled vocabulary and free-text terms for “acute pancreatitis,” “albumin,” and “acute kidney injury”." (PMID 41523521, 2025). "In conclusion, the present study revealed that HDF using a vitamin E‐coated hemodiafilter rescued the reduction of serum albumin and increased RedALB levels in a pig model of acute kidney injury." (PMID 40108938, 2025). "The present study demonstrated that HDF performed using a vitamin E‐coated hemodiafilter effectively minimized the reduction in serum albumin and RedALB levels compared to the vitamin E‐non‐coated hemodiafilter in an acute kidney injury pig model." (PMID 40108938, 2025).
acute kidney injury (continued). "Complications of idiopathic nephrotic syndrome include acute kidney injury, thromboembolic events (1.5–3.8% in children), and life-threatening hypovolaemia, particularly during relapses when albumin levels drop below 20–25 g/L." (PMID 40283525, 2025). "Other investigators have studied the predictive value of the CRP/albumin, PCT/albumin, and IL-6/albumin ratios, focusing on 30-day mortality rates and acute kidney injury." (PMID 41302121, 2025). "In dialysis‐dependent acute renal failure, the levels of antioxidant vitamins such as α‐tocopherol were reduced and directly correlated with albumin and total antioxidant capacity of serum (ex." (PMID 40108938, 2025). "According to studies, urinary L-FABP concentration was significantly higher in patients with T2D who had normal urinary albumin concentration compared to normal control group in the case of renal failure." (PMID 41155157, 2025). "The neutrophil percentage to albumin ratio (NPAR), a composite biomarker derived from neutrophil and albumin levels, has demonstrated efficacy in predicting inflammation in various conditions, such as acute kidney injury, septic shock, and rectal cancer." (PMID 39917306, 2025). "Fluid imbalance also alters albumin concentration, and a portion of the renal failure patients in this study had fluid retention, which led to a decrease in albumin concentration." (PMID 40415246, 2025). "Previous studies have shown that oxidized albumin levels increase in liver failure and renal failure, suggesting its potential as a marker of systemic oxidative status." (PMID 40502874, 2025). "Laboratory data showed significantly low albumin, protein, acute kidney injury, and several electrolyte abnormalities." (PMID 38618465, 2024). "A Cox proportional hazards model revealed that old age, acute kidney injury at presentation, increased total leukocyte counts, low platelet counts, decreased albumin levels, and increased LDH levels were the independent predictors of mortality." (PMID 38639116, 2024). "It appears albumin decreases the incidence of acute kidney injury (AKI); however, meta-analysis studies show an increased need for post-operative renal replacement therapy." (PMID 40822573, 2024). "The cohort characterized by persistently low albumin levels exhibited the highest likelihood of developing acute kidney injury and fluid accumulation, with their shorter ICU stay potentially attributable to an increased mortality rate within a brief period." (PMID 39101009, 2024). "A left renal vein thrombosis was discovered, revealing nephrotic syndrome with a serum albumin concentration of 15.8 g/L and albuminuria at 8 g/24 h, complicated by acute renal failure, with creatinine levels escalating from 44 μmol/L to 142 μmol/L." (PMID 38540991, 2024). "PAR, the PLT divided by the ALB, was proven to be positively closely related to the severity and prognosis of many inflammatory diseases, such as ankylosing spondylitis disease, acute kidney injury, periprosthetic joint infection." (PMID 38785171, 2024). "Albumin is a common and multifunctional protein that predicts prognosis in various diseases, such as infections, acute renal failure, and acute coronary syndromes." (PMID 38326383, 2024). "The dosage of albumin was 40 g of 20% albumin for 15 days or until there was a primary end-point event (renal failure, hyponatremia, infections, hepatic encephalopathy, or gastrointestinal bleeding)." (PMID 38551716, 2024). "The incidences of acute kidney injuries were 63.93% in patients treated with antibiotics only and 33.33% in patients treated with a combination of antibiotics and albumin." (PMID 38551716, 2024). "This is because renal failure reduces the concentration of albumin in the blood; since albumin binds to calcium, its reduction makes calcium levels appear high." (PMID 38360579, 2024).
acute kidney injury (continued). "Previous studies have reported that Nam can reduce urinary albumin excretion in preeclampsia mice, and preserve renal function in mice with acute kidney injury." (PMID 38446387, 2024). "Our study has revealed significant disparities in the duration of ICU stay, the length of mechanical ventilation, and the incidence of acute kidney injury and fluid accumulation among patient cohorts with divergent serum albumin trajectories." (PMID 39101009, 2024). "The NPAR, which combined the NLR and albumin, is used as a systemic inflammation-based predictor in patients with palliative pancreatic cancer, acute kidney injury, and septic shock." (PMID 37111111, 2023). "High ALAT reflects liver pathology, high albumin and high urea a state of dehydration or hemo-concentration and renal failure." (PMID 37957690, 2023). "Stem cell-derived exosomes have been shown to significantly reduce the levels of blood urea nitrogen (BUN), serum creatinine (SCR), urine albumin and creatinine (ACR), and 8-isoprostane associated with renal failure." (PMID 36937479, 2023). "Increases in albumin fragments in the blood due to albumin proteolysis have been described in some diseases such as renal failure." (PMID 37092455, 2023). "The association between the total bilirubin/albumin (B/A) and the all-cause mortality of critically ill patients with acute kidney injury (AKI) remains unclear." (PMID 37910573, 2023). "Previous studies on the pathogenesis of acute renal failure have demonstrated that NF-κB inhibitors can significantly reduce the production of IL-1β and IL-18 in albumin-stimulated HK-2 cells." (PMID 36732854, 2023). "Increases in acute kidney injury markers were observed after all experiments, but changes in urine albumin and cystatin C were highest after xylitol." (PMID 36338481, 2022). "Patients in group 2 were sicker with higher PT (INR), urea, creatinine, CTP, and MELD score and low serum sodium, albumin, and platelet count with a higher prevalence of variceal bleed, hepatic encephalopathy, and acute kidney injury." (PMID 35800810, 2022). "We hypothesized that kidney function, presence of acute kidney injury (AKI), serum albumin, and hemoglobin would be associated with and predict PRES in high-risk children." (PMID 35142281, 2022). "Another trial, including 193 cirrhotic patients with infection other than SBP (spontaneous bacterial peritonitis) in 2015, also negated the benefit of albumin infusion in overall patient survival and improvement of renal failure." (PMID 35721190, 2022). "While traditional indicators of kidney function, including eGFR, serum creatinine, and albumin-to-creatinine ratio are used to diagnose acute kidney injury or CKD, newer biomarkers hold the potential of detecting renal damage at earlier stages." (PMID 36422900, 2022). "This health problem is characterized by increased urinary albumin excretion, leading to decreased glomerular filtration rate and renal failure." (PMID 35787282, 2022). "Diabetic nephropathy manifests as increased urine albumin excretion, decreased estimated glomerular filtration rate (eGFR), and renal failure." (PMID 35787282, 2022). "Although it was previously revealed that the abnormalities of renal function resulting in renal failure are common in thalassemic patients, serum albumin, calcium, phosphorus, creatinine, and BUN are commonly normal in these patients." (PMID 35622784, 2022). "Renal outcomes showed a significant lowering of risk of acute kidney failure, progression of CKD, renal mortality, and improvement in urinary albumin creatinine ratio." (PMID 34650848, 2021). "The amounts of albumin in plasma of mild and severe renal failure model rats were significantly lower than those in normal rats." (PMID 34945005, 2021). "Preeclampsia-associated renal dysfunction accounts for proteinuria with an increased albumin-creatinine ratio and/or other markers of acute kidney injury." (PMID 34685589, 2021).
acute kidney injury (continued). "There are variety of severity scores that asses the severity of CDI early in the course of the disease, based on expert opinion, which includes leukocytosis, low albumin levels, and creatinine levels or acute kidney injury." (PMID 34209348, 2021). "Another possible mechanism for increased urinary albumin is related to expression of the normal silent albumin gene in proximal tubules, as observed during acute kidney injury." (PMID 34884436, 2021). "In the early stage, DN manifests clinically as microalbuminuria (defined as a urinary albumin excretion rate of 20–200 μg/min), followed by macroalbuminuria and renal failure with the progression of the disease." (PMID 33427556, 2021). "The highest HBP-to-albumin ratio and HBP levels were significantly associated with development or worsening of acute kidney injury, positive fluid balance, and levels of inflammatory cytokines." (PMID 33925831, 2021). "Albumin administration appeared to improve renal failure in liver dysfunction, which can contribute to preventing the deterioration of liver dysfunction and lead to recovery." (PMID 34351969, 2021). "In the context of SBP, the administration of albumin (1.5 g/kg b.w. at diagnosis and 1 g/kg b.w. on day 3) significantly reduces the development of renal failure and the in-hospital and 3-month mortality [45•]." (PMID 32837825, 2020). "Additionally, a study of patients undergoing cardiac surgery using a propensity score-matching method showed that albumin was dose-dependently associated with increasing risk of acute kidney injury (AKI)." (PMID 32783070, 2020). "Given the variability of drug protein binding in ICU patients with low albumin levels and renal failure, the main purpose of this study was to develop a reliable and sensitive method based on UPLC coupled with quadrupole‐linear ion trap MS/MS." (PMID 31785116, 2020). "In acute kidney injury, DXM causes high blood ALB levels and proteinuria and has a long-term effect on renal glomerular filtration." (PMID 33332210, 2020). "The effect of hypoalbuminemia for cefuroxime dosing in critically ill patients with low levels of albumin or renal failure is likely to have significant consequences on the drug's pharmacodynamics (PD) and pharmacokinetics (PK)." (PMID 31785116, 2020). "Approximately 50% of these transgenic mice developed spontaneous LN by 3–4 weeks of age, as evidenced by the sudden appearance of proteinuria and glomerular albumin leakage, and succumbed to renal failure within approximately 2–3 weeks thereafter." (PMID 32870819, 2020). "Patients with ischemic hepatitis were more likely to have metabolic acidosis, renal failure, and low albumin, which are suggestive of a more severe pathology." (PMID 32280751, 2020). "The design and targeted samples extremely varied, which using surrogate markers of renal damage, renal function decline, urine albumin excretion rate, or renal failure." (PMID 31580172, 2019). "One of the first observations in nephrology was done by Bright who found not only urea retention but also presence of albumin in urine in patients with renal failure." (PMID 31661892, 2019). "The study found that terlipressin plus albumin is significantly more effective than midodrine and octreotide plus albumin in reversal of renal failure (55.5% vs 4.8%, P < .001) and improving renal function (70.4% vs 28.6%, P = .01) in patients with HRS." (PMID 29668606, 2018). "They found higher serum phosphorus level and lower serum albumin level in renal failure group compared with non-renal failure group (1.85 vs 1.06 mmol/L, P<0.001 and 30.8 vs 35.9 g/L, P=0.010)." (PMID 29392076, 2018). "Within the propensity-matched patients, 20.3%, 2.9%, and 4.4% of hyperoncotic albumin-exposed patients experienced stages 1, 2, and 3 of acute kidney injury, as compared to 19.6%, 2.5%, and 3.0% of control patients." (PMID 30564306, 2018).